MIR301A (microRNA 301a)
Synonyms: hsa-mir-301; hsa-mir-301a; MIR301; MIRN301; MIRN301A; mir-301a
Gene: MicroRNA gene on chromosome 17 (59,151,136 to 59,151,221, reverse strand). Ensembl gene ENSG00000207996.
Homologues: Orthologues: chimpanzee ptr-mir-301a (100% identical), macaque mml-mir-301a (100% identical), rabbit MIR301A (100% identical), rat Mir301a (84% identical), guinea pig MIR301A (83% identical), zebrafish dre-mir-301a-1 (83% identical), pig MIR301A (77% identical), tropical clawed frog xtr-mir-301-1 (77% identical). Paralogues in human: MIR301B (62% identical), MIR130A (53% identical).
Diseases named in the same sentence as MIR301A in open-access papers:
MIR301A is named in the same sentence as 3 diseases in open-access papers, as found by Europe PMC text mining. Sharing a sentence is not in itself a finding about the gene and the disease. The quoted sentences say what the papers report.
gastric cancer (1 paper, 2022). A primary or metastatic malignant neoplasm involving the stomach. "For example, in a study, 5 exRNAs, including 3 mRNAs (SPINK7, PPL, and SEMA4B) and 2 microRNAs (MIR140-5p and MIR301a), showed downregulation in gastric cancer (GC)." (PMID 35948986, 2022).
MIR301A also shares sentences with these, for which no sentence is quoted: kidney cancer (1 paper); prostate carcinoma (1).